OR5M1 (olfactory receptor family 5 subfamily M member 1)
Description:
Odorant receptor.
Synonyms: OST050; OR11-208
Tractability: Antibody: UniProt places it where antibodies can reach, with medium confidence; UniProt predicts a signal peptide or a membrane-spanning region; its Gene Ontology location is reachable by antibodies, with medium confidence.
Gene: Protein-coding gene on chromosome 11 (56,609,236 to 56,614,874, reverse strand). Ensembl gene ENSG00000255012.
Subcellular location: Cell membrane
Pathways (Reactome):
Sensory Perception: Expression and translocation of olfactory receptors
Gene Ontology:
Molecular function: olfactory receptor activity; G protein-coupled receptor activity
Biological process: G protein-coupled receptor signaling pathway; sensory perception of smell; detection of chemical stimulus involved in sensory perception of smell
Cellular component: plasma membrane; membrane
Genetic constraint (gnomAD): Loss-of-function variants: 0 observed, 0.12 expected, observed/expected ratio (o/e) 0, 90% interval 0 to 1.89. That is too few expected variants to judge how well the gene tolerates losing a copy. Missense variants: 367 observed, 382 expected, observed/expected ratio (o/e) 0.96, 90% interval 0.88 to 1.05. Synonymous variants: 165 observed, 143.64 expected, observed/expected ratio (o/e) 1.15, 90% interval 1.01 to 1.31.
Homologues: Orthologues: chimpanzee OR5M1 (98% identical), dog OR5M10 (86% identical), rat Or5m10b (82% identical), mouse Or5m10 (82% identical), rat Or5m10 (82% identical), mouse Or5m10b (80% identical). Paralogues in human: OR5M10 (96% identical), OR5M11 (65% identical), OR5M8 (62% identical), OR5M3 (57% identical), OR5M9 (56% identical), OR5B12 (52% identical), OR8U1 (52% identical), OR9G4 (52% identical), OR5AR1 (51% identical), OR5B21 (51% identical), OR8U3 (51% identical), OR8I2 (50% identical), and 84 more.